RACGAP1 (Rac GTPase activating protein 1)
Diseases named in the same sentence as RACGAP1 in open-access papers (continued):
Sharing a sentence is not in itself a finding about the gene and the disease.
tumor (continued). "In the meantime, a significant decrease in average tumor weight (1.5 ± 0.21 g vs. 0.65 ± 0.14 g) and reduced cell proliferation, assessed by Ki67 IHC, were also observed in RACGAP1 knockdown xenograft." (PMID 38898473, 2024). "RACGAP1 not only indicates poor prognosis and limited immunotherapy benefits but also serves as a potential targeted biomarker influencing tumor stemness." (PMID 38167018, 2024). "Online database analysis revealed a significant increase in RACGAP1 mRNA expression among 26 types of tumor tissues, including LUAD tissues." (PMID 38622149, 2024). "With radical cystectomy for patients as the source of urothelial carcinoma of the bladder, RACGAP1 shows a correlation with the tumor size in support of its role as a prognostic factor for overall survival." (PMID 39858398, 2024). "The mean tumor volume at 653.3 ± 73.39 mm3 in RACGAP1 low expression C4-2B-ENZR xenografts but 1367 ± 273.3 mm3 in the control group." (PMID 38898473, 2024). "Combination of enzalutamide and in vivo cholesterol-conjugated RIG-I siRNA drugs targeting RACGAP1 induced potent inhibition of xenograft tumor growth of PCa." (PMID 38898473, 2024). "In vivo experiments were conducted to evaluate the effect of RACGAP1 inhibition on the tumor growth." (PMID 38898473, 2024). "In conclusion, our findings suggest that RACGAP1 contributes to tumor progression and unfavorable prognosis by affecting the cell cycle and tumor stemness." (PMID 38167018, 2024). "Immunohistochemical staining and Western blotting were used to observe the expression of risk model factors PRR11, KIF11, RACGAP1 as well as the potential common transcription factors YY1, CREB1 and SUZ12 in HCC tissues and para-tumor tissues." (PMID 39530087, 2024). "As a novel tumor proto-oncogene, overexpression of RACGAP1 was related to the occurrence of various tumors." (PMID 38898473, 2024). "Our last differential comparison was based on the RACGAP1 protein level analysis in normal and tumor tissues." (PMID 36430577, 2022). "As a novel tumor protooncogene, overexpression of RacGAP1 was related to the occurrence of various tumors, but its function in CC is still unclear." (PMID 35831303, 2022). "Given the significant role of RACGAP1 in oncogenic development and tumor recurrence, the regulatory mechanism related to RACGAP1 is well worthy of attention." (PMID 35013128, 2022). "The “compare tumor, normal, and metastasis” module of the TNMplot online server was then utilized to correlate the RACGAP1 mRNA expression levels with the metastases." (PMID 36430577, 2022). "The lncRNA MAGI2-AS3 interacts with KDM1A and promotes histone demethylation of histone H3 lysine 4 (H3K4me2) in the RACGAP1 promoter region, and silencing RACGAP1 inhibits tumor growth in vivo." (PMID 35205612, 2022). "In our study, it was found that miR-192 was negatively correlated with RacGAP1 and suppressed tumor malignant progression." (PMID 35831303, 2022). "Analysis of MDSC infiltration, a cell with immunosuppressive functions in tumor, in the panel of TCGA tumors showed that more than 80% of the studied tumors experienced a positive correlation between RACGAP1 expression and MDSC infiltration." (PMID 36430577, 2022). "For this purpose, it was important to study the correlation between elevated RACGAP1 expression in tumor tissue and the tumor infiltration of different types of immune cells." (PMID 36430577, 2022). "Yuan at al. confirmed that ASPM, FOXM1, RACGAP1, and TPX2 were significantly associated with not only tumor progression but also prognosis of ACC." (PMID 35693556, 2022). "RACGAP1 expression was significantly elevated in the breast, kidney, and liver when normal and tumor tissues were compared, and this pattern was also maintained between metastatic and cancerous tissues." (PMID 36430577, 2022). "For this purpose, we tried to find a correlation between the upregulation of RACGAP1 in tumor tissue and those promising biomarkers." (PMID 36430577, 2022).
tumor (continued). "Analysis of RACGAP1 correlated proteins in the tumor tissue revealed that POLR3C, PRKAB2, SETDB1, GPATCH4, and MSTO1 were the top five." (PMID 36430577, 2022). "First, we tried to find the correlation between RACGAP1 expression and the infiltration of two types of immune cells with opposing roles against tumor growth." (PMID 36430577, 2022). "Further research showed that miR-192, which plays as a tumor suppressor in CC, was identified as a downstream target of RacGAP1 in CC cells." (PMID 35831303, 2022). "The mean tumor size of high RACGAP1 group and low RACGAP1 group were 3.665±1.869 cm and 2.469±1.495 cm, respectively (P<0.05)." (PMID 34239347, 2021). "Consistent with in vitro data, RACGAP1 shRNA group displayed a significant tumor growth inhibition as volume and weight were only 20% and 25%, respectively, of those in the control group." (PMID 34239347, 2021). "The elevated level of RACGAP1 correlated to the clinical progression of GBC including tumor size, tumor invasion, and a poorer overall survival." (PMID 34239347, 2021). "We found that four of the hub genes (TOP2A, AURKA, NEK2, and RACGAP1) can serve as tumor therapeutic targets for drugs approved by FDA." (PMID 33946043, 2021). "Previous studies reportedthe overexpression of RACGAP1 lead to gastric, ovarian, colorectal, and several other cancers, implying its role in promoting tumor progression." (PMID 35540695, 2021). "To conclude, our study shows, for the first time, the tumor-promoting role of RACGAP1 in GBC which is partially mediated by binding to and stabilizing LIG3." (PMID 34239347, 2021). "Events related to a single gene, such as WNK1,FBLN5 and RACGAP1, exhibited opposite patterns between tumor and normal samples, indicating that an uneven distribution in the splicing patterns plays different roles in cancer development." (PMID 34130646, 2021). "QPCR analysis confirmed that the average expression of RACGAP1P and RACGAP1 was much higher in RACGAP1P 3’UTR overexpressing tumour tissues compared with control tumours." (PMID 31160556, 2019). "We also found that CGN treatment following radiotherapy effectively suppressed the expression of RacGAP1 in in vitro cell culture and in vivo mouse tumor model." (PMID 31426369, 2019). "All investigated tumor samples showed mainly nuclear staining of the RACGAP1 protein in at least 30% of the tumor cells." (PMID 26778597, 2016). "The RT‐PCR data confirmed a strong correlation of AURKA and RACGAP1 gene expression both in the tumor, the tumor‐adjacent and the tumor‐distant mucosa." (PMID 26778597, 2016). "RacGAP1 expression levels were, in general, lower than those of the other two markers, but a high expression rate was present at the invasive front of some tumor samples." (PMID 27259241, 2016). "In the tumor‐adjacent mucosa, this was confirmed only for RACGAP1 and CTNNB1 (r = 0.401, P = 0.003)." (PMID 26778597, 2016). "Presence of the RACGAP1 protein correlated with age, tumor size, and stage of disease with RACGAP1 expression representing an indicator of poor prognosis." (PMID 26778597, 2016). "There was a positive correlation of AURKA with RACGAP1 gene expression in the tumor (r = 0.539, P < 0.001)." (PMID 26778597, 2016). "In the tumor tissue there was a weak positive correlation of RACGAP1 gene expression with CTNNB1 (r = 0.288, P = 0.033), as well as an inverse association with CDKN1A gene expression (r = −0.357, P = 0.012)." (PMID 26778597, 2016). "Little is known about RacGAP1, except that it is involved in the cytokinesis, migration, cell motility, and transformation of tumor cells, and subsequent increased metastasis." (PMID 27259241, 2016). "RacGAP1 is involved in cytokinesis, cell transformation, invasion, migration, and differentiation; it is also involved in tumorigenesis, and tumor progression, metastasis, and recurrence." (PMID 27259241, 2016).
tumor (continued). "RACGAP1 silencing could inhibit tumor cells survival and promote ferroptosis, and such anti-tumor activity could be blocked by ferroptosis inhibitors." (PMID 41444950, 2025). "The anti-tumor activity of RACGAP1 silencing was blocked by ferroptosis inhibitors, suggesting that RACGAP1 could inhibit TNBC cells survival by sensitizing TNBC cells to ferroptosis." (PMID 41444950, 2025). "Importantly, RacGAP1 expression was also correlated with several unfavorable prognostic factors, including tumor size (p = 0.001) and lymph node metastasis (p = 0.02)." (PMID 40497948, 2025). "Moreover, RacGAP1 expression increased along the tumor stage, particularly in stage IV, which is the most advanced stage with metastasis or cancer spread, to the lining of the lung or other areas of the body." (PMID 40497948, 2025). "Furthermore, we found a clear correlation between elevated RacGAP1 expression and unfavorable prognostic factors such as tumor size and lymph node metastasis." (PMID 40497948, 2025). "Additionally, the protein levels of RacGAP1 in LUAD patients were evaluated through the analysis of Clinical Proteomic Tumor Analysis Consortium (CPTAC) samples using the University of ALabama at Birmingham CANcer Data Analysis Portal (UALCAN)." (PMID 40497948, 2025). "Knockdown of RACGAP1 suppressed the migration, proliferation, and tumor growth of cancer cells." (PMID 38167018, 2024). "Importantly, the combination of RACGAP1 inhibition and enzalutamide significantly inhibited tumor progression, suggesting a promising therapeutic strategy for overcoming endocrine treatment resistance in PCa." (PMID 38898473, 2024). "Additionally, experimental evidence has demonstrated that low expression of RACGAP1 favors tumor cell apoptosis and restoration of the cell cycle, while high expression promotes invasion and metastasis." (PMID 38947404, 2024). "RACGAP1 inhibition could break down this feedback loop, resulting in tumor suppression and re-sensitization of enzalutamide treatment." (PMID 38898473, 2024). "RACGAP1 expression was significantly greater in tumor tissues than in adjacent normal tissues." (PMID 38622149, 2024). "Patients with high tumor RACGAP1 expression had shorter relapse-free survival time." (PMID 37196108, 2023). "Among them, after DG exposure, standouts include the strong downregulation (logFC = −4) of GTPase activating protein 1 (RACGAP1) and Rho GTPase activating protein 35 (ARHGAP35), which are putative oncoproteins whose overexpression is linked with different tumor types." (PMID 37755964, 2023). "One recent research emphasized that Radiotherapy, frequently used to cancer treatment, might reduce tumor cell activity and restrained capacity of invasion and metastasis by down-regulation of RACGAP1." (PMID 35958019, 2022). "Additionally, CpG aggregated methylation data revealed that all of the significant results favored RACGAP1 hypomethylation in the tumor sample versus the normal one (except for CHOL)." (PMID 36430577, 2022). "We also detected the role of PRC1 and RACGAP1 in tumor metastasis." (PMID 35445033, 2022). "The result manifested that RACGAP1 had higher expression in HCC compared with non-tumor tissues." (PMID 35958019, 2022). "Additionally, we investigated the mutation forms, the correlation with several immune cell infiltration, the phosphorylation status of the interested protein in normal and tumor tissues, and the potential molecular mechanisms of RACGAP1 in cancerous tissue." (PMID 36430577, 2022). "Compared with sh-NC group, tumor size and weight were obviously diminished in sh-RACGAP1." (PMID 35958019, 2022). "Moreover, it was found that RACGAP1 affects the tumor immune microenvironment by influencing the infiltration level of several immune cells." (PMID 36430577, 2022). "RACGAP1 mRNA was markedly upregulated in tumor samples in contrast to matched controls (P = 0.026)." (PMID 34239347, 2021).
tumor (continued). "However, the staining intensity or the range of positive areas of CEP55, KIF23, MYBL2, and RACGAP1 was higher in tumor samples (medium or high levels) than in non-tumor tissue." (PMID 34093635, 2021). "Gene knockdown of RACGAP1 hindered tumor cell proliferation and survival both in vitro and in vivo." (PMID 34239347, 2021). "Moreover, ROC curves revealed that CENPF and RACGAP1 exhibited robust discrimination between tumor and normal tissue samples." (PMID 33946043, 2021). "Among these, RACGAP1, RARRES3, TPX2, MMP28, GPR87, and KIF14 were upregulated and positively associated with poor survival, whereas TSPAN7 was downregulated and identified as a tumor suppressor." (PMID 33033514, 2020). "Moreover, RacGAP1 is recently reported to have important roles in oncogenic activity, tumor progression, and cancer invasion." (PMID 31426369, 2019). "Taken together, these results indicate that adjuvant CGN treatment effectively suppresses primary tumor growth and reduces metastatic potential, which may be the result of RacGAP1 suppression." (PMID 31426369, 2019). "The expression of LMNB1, TK1, ZWINT, and RACGAP1 was positively associated with tumor purity, while no or weak associations were observed for hub genes and infiltrating immune cells in PCa tissue samples." (PMID 31306099, 2019). "Specifically, RACGAP1 silencing markedly reduced the tumor weight and volume as well as the expression of proliferation marker Ki67 of the tumor-bearing mice, while such anti-tumor effects of RACGAP1 silencing were partly counteracted by ferroptosis inhibitor ferrostatin-1 treatment." (PMID 41444950, 2025). "RACGAP1 may have an effect on tumor stemness in LUADs and promote proliferation and migration." (PMID 39858398, 2024). "In this study, the reduction of RACGAP1 expression was followed by western blot, which revealed that the stem cell biomarkers KI-67 and Nanog were similarly reduced in expression, suggesting a potential regulatory relationship between RACGAP1 and the tumor stemness phenotype." (PMID 38167018, 2024). "Meanwhile, down-regulation of RACGAP1 could suppressed tumor growth through the tumor growth curve." (PMID 35958019, 2022). "Interestingly, LMNB1, RACGAP1, TK1, and ZWINT were all positively associated with tumor purity." (PMID 31306099, 2019). "Western blotting revealed significantly elevated levels of CCNA2, CSRP2, ILF2, KIF2C, RACGAP1, and VARS proteins in HCC tissues compared to adjacent non-tumor tissues." (PMID 41323394, 2025). "Western blot analysis substantiated these findings at the protein level, revealing significantly elevated expression of CCNA2, CSRP2, ILF2, KIF2C, RACGAP1, and VARS in HCC tissues versus adjacent non-tumor tissues." (PMID 41323394, 2025). "A heatmap of the 11 mRNA expression levels of the tumor samples displayed that the seven genes, including CCNB1, CCNB2, CHEK1, FEN1, PTTG1, RACGAP1, and UBE2C, had higher expression levels in the tumor tissue." (PMID 41009526, 2025). "The expression levels of G6PD, HMGA1, MKI67, RACGAP1, and RFC4, were significantly higher in tumor samples with (p < 0.05)." (PMID 40421085, 2025). "To verify the anti-tumor effect of sh-RACGAP1 in vivo, we established xenograft tumor models by subcutaneously injecting MDA-MB-231 cells, and MDA-MB-231 cells transfected with NC, sh-RACGAP1 and sh-RACGAP1 + oe-CPT1A, respectively." (PMID 41444950, 2025). "As for ferroptosis markers, RACGAP1 silencing markedly reduced the expression of GPX4, while increased the tumor tissue iron content, serum iron content and serum peroxidation MDA level." (PMID 41444950, 2025). "Our examinations showed a significant overexpression of five genes (CCNB1, CCNB2, PTTG1, RACGAP1, and UBE2C) in the tumor samples." (PMID 41009526, 2025).
tumor (continued). "We identified six signature LRGs (ALB, G6PD, HMGA1, MKI67, RACGAP1, and RFC4) possess prognostic potential, correlation with immune infiltration, and lactylation-related pathways, providing novel insights into tumor microenvironment (TME) of HCC." (PMID 40421085, 2025). "IHC score indicated that PRR11, KIF11, RACGAP1, YY1, CREB1 expression was significantly increased in HCC tissues compared to adjacent para-tumor tissues." (PMID 39530087, 2024). "We then verified that RACGAP1 could promote the tumor stemness phenotype and the rapid proliferation of tumor cells through cell phenotyping experiments and in vivo experiments in animals, which implies that RACGAP1 may serve as a potential therapeutic target for targeted stem cell therapy." (PMID 38167018, 2024). "The high expression of RACGAP1 in NEPC tissues was positively correlated with the stage and grade of the tumor and suggested a poor prognosis of patients." (PMID 37196108, 2023). "To explore the expression difference of RACGAP1 between HCC and non-tumor tissues, we used 70 paired HCC tissues to conduct RT-PCR." (PMID 35958019, 2022). "We conclude that RACGAP1 exerts a tumor-promoting role via binding LIG3 to reduce apoptosis and facilitate cell growth in GBC, pointing to RACGAP1 as a potential therapeutic target for GBC." (PMID 34239347, 2021). "Next, we systematically explored the relationship between the expression of 37 common DEGs in tumor tissues and OS rate in TCGA and constructed a novel prognosis-related model composed of five genes (AURKA, PZP, RACGAP1, ACOT12 and LCAT)." (PMID 34336648, 2021). "Among these DE-MTGs, upregulated RACGAP1, RARRES3, TPX2, MMP28, GPR87, and KIF14 with HR > 1 were regarded as oncogenes, whereas downregulated TSPAN7 with HR < 1 was regarded as a tumor suppressor." (PMID 33033514, 2020). "MGI is a gene expression assay, measuring the expression of five genes (BUB1B, CENPA, NEK2, RACGAP1, RRM2) related to histological grade and tumor progression, which recapitulates tumor grade and can predict the clinical outcome with high performance." (PMID 33287297, 2020). "Consistent with the results of integrated analysis, mRNA expression of RACGAP1, RARRES3, TPX2, MMP28, GPR87, and KIF14 was significantly upregulated in PDAC tumor tissues, whereas TSPAN7 was significantly downregulated." (PMID 33033514, 2020). "In this study, we identified RACGAP1 as an oncogene in TNBC, and its silencing could effectively inhibit the tumor growth and progression of TNBC by enhancing ferroptosis." (PMID 41444950, 2025). "Besides, sh-RACGAP1 group showed highest level of 4-HNE, a ferroptosis marker indicating cytotoxic lipid peroxidation, and highest iron content in tumor tissue than control and sh-NC groups, while such changes were partly blocked by CPT1A overexpression." (PMID 41444950, 2025). "We also found that putative tumor suppressors, such as FOXP1, STK4, and ATM were frequently hypermethylated and silenced whereas oncogenes, such as UHRF1, MPZL1, CDK14, RACGAP1, and RAB13, were hypomethylated and overexpressed suggesting that DNA methylation changes contribute to PTCL development." (PMID 38464090, 2024). "Recently, it was reported that patients with RacGAP1 (Rac GTPase activating protein 1) expression in the invasive front of the tumor exhibited a significantly poorer prognosis than those without RacGAP1 expression." (PMID 35110666, 2022). "Another interesting finding is that not even one tumor in our analyzed list experienced a positive between RACGAP1 expression and NKT infiltration." (PMID 36430577, 2022). "To validate this finding, we investigated RacGAP1 mRNA expression in 30 paired fresh tumor tissues and their paired adjacent noncancerous tissues by qRT-PCR and the protein expression in 64 paired CC and normal samples by Western blot." (PMID 35831303, 2022).